DES (desmin)
Diseases named in the same sentence as DES in open-access papers (continued):
Sharing a sentence is not in itself a finding about the gene and the disease.
dilated cardiomyopathy (32 papers, 2009 to 2026). Cardiomyopathy which is characterized by dilation and contractile dysfunction of the left and right ventricles. "The DES p.R355* variant identified in our patient has been entered in ClinVar four times in association with “dilated cardiomyopathy”, “cardiac manifestations”, and “desmin-related myofibrillar myopathy”." (PMID 40574817, 2025). "For example, in rat studies, a deficiency in desmin synthesis was found to cause dilated cardiomyopathy, smooth muscle defects, and skeletal myopathy." (PMID 39062865, 2024). "In human literature, dilatated cardiomyopathy is associated with mutation of dystrophin and tafazzin, cardiac actin, desmin and laminin A/C and also the sarcoglycans, in particular delta-sarcoglycan." (PMID 37628692, 2023). "Its importance for cardiac homeostasis has been clearly manifested by the development of mitochondrial defects, oxidative stress, myocardial remodeling, dilated cardiomyopathy, and HF in desmin-deficient mice." (PMID 31001541, 2019). "Mutation or knockout of desmin frequently causes dilated cardiomyopathy, a heart disease that often develops in the end stage of viral myocarditis." (PMID 24722419, 2014). "In a study on the prevalence of desmin mutations in a cohort of 116 families and 309 additional patients with pure dilatative cardiomyopathy, desmin mutations accounted for up to 2 % of disease manifestation." (PMID 23143191, 2013). "Mutations in the desmin gene have been associated with dilated cardiomyopathy." (PMID 41163301, 2025). "Interestingly, a similar phenotype describing loss of Cx43 localization to the intercalated disc coupled with desmin aggregation has been described in D7-des mice, which encode a deletion that causes human dilated cardiomyopathy." (PMID 22905185, 2012). "Immunohistochemical analysis showed abnormal expression patterns of desmin, vimentin, and connexin 43, similar to those previously reported in humans and dogs with dilated cardiomyopathy." (PMID 42110576, 2026). "The dilated cardiomyopathy (DCM) pathway involves proteins such as Desmin, DMD, Titin, Tnt, ACTA1, TPM, Laminac, SGCD, TNF-α, IGF-1, TGF-β, and Ang-II." (PMID 32419790, 2020). "These mice developed an age-dependent desmin-positive protein aggregation pathology, skeletal muscle weakness, dilated cardiomyopathy, as well as cardiac conduction defects and arrhythmias." (PMID 31835587, 2019). "As a surrogate, we used our homozygous R349P DKI mice, which show desmin protein aggregate pathology as well as a cardiac phenotype comprising conduction defects, arrhythmias, and a late-onset dilated cardiomyopathy." (PMID 32322014, 2019). "These mice develop age-dependent desmin-positive protein aggregation pathology, skeletal muscle weakness, dilated cardiomyopathy, as well as cardiac arrhythmias and conduction defects." (PMID 25394388, 2015). "Prior work in myocardial samples from human ICM has demonstrated increased abundance of short fibrils of desmin (~190 kD), which mimic preamyloid oligomers detectable with A11 staining in patients with dilated cardiomyopathy and mice with transgenic expression of R120G mutant CRYAB." (PMID 39932799, 2025). "Over the past years, more than 70 human diseases and cardiomyopathies have been modeled using iPSC-derived cells, including cardiac sodium channel diseases, the long QT syndrome, a desmin-related dilated cardiomyopathy, Barth syndrome and Duchenne muscular dystrophy." (PMID 31001541, 2019). "Interestingly, homozygous null desmin mice have been shown to develop cardiomyocyte hypertrophy and dilated cardiomyopathy characterized by extensive myocyte cell death, calcific fibrosis, and multiple ultrastructural defects." (PMID 23815709, 2013). "Interestingly, the expression levels of desmin in the heart have been shown to increase in HCM/diastolic dysfunction mouse models and decrease in dilated cardiomyopathy (DCM) models." (PMID 35032456, 2022).
dilated cardiomyopathy (continued). "It has been reported a heart without desmin is characterized by cardiomyocyte degeneration and a dilated cardiomyopathy." (PMID 34567153, 2021). "Mice lacking desmin develop dilated cardiomyopathy approximately starting 8 months after birth (6 months after injection)." (PMID 32322014, 2019).
myofibrillar myopathy (32 papers, 2011 to 2026). "It was puzzling that GFPT1 defect in patient one was associated with atypical pathological changes of myofibrillar myopathy (MFM) characterized by desmin deposits, Z‐disc disorganization, and electronic dense granulofilamentous aggregation." (PMID 34978387, 2022). "The DRM represents a subgroup of myofibrillar myopathy where myopathic manifestations of disease are caused mainly by mutations in desmin or HSPB5 (also known as αB-crystallinopathy)." (PMID 35164412, 2022). "We found abnormal aggregations of the intermediate filament desmin, the myofibrillar protein myotilin, and the chaperone alpha-crystallin B, all three mutated in myofibrillar myopathies." (PMID 31455395, 2019). "HIBM1 is now referred to desmin-related myofibrillar myopathy, which is caused by a mutation in the desmin gene." (PMID 22723986, 2012). "Genetic mutations in the intermediate filament protein desmin also cause mis-assembly and aggregation of desmin, resulting in myofibrillar myopathy having similar pathological features." (PMID 21423662, 2011). "METHODS: Therefore, we investigate in this study the impact of an uncharacterized myofibrillar myopathy-associated desmin variant (p.T341P) on filament assembly in transfected cells and performed atomic force microscopy to characterize in vitro the filament assembly of recombinant desmin-p.T341P." (PMID 41880120, 2026). "Analysis by electron microscopy (EM) demonstrated disruption of the contractile apparatus with Z-band disruption and accumulated intermyofibrillar filamentous material very similar to what is known from genetic myofibrillar myopathies, e.g., autosomal dominant desmin mutations." (PMID 39012547, 2024). "These mutations have been associated with myofibrillar myopathy, restrictive cardiomyopathy, and hypertrophic cardiomyopathy and promote pathological hypertrophy through different mechanisms such as desmin aggregation, increased reductive stress, or activation of calcineurin–NFAT signaling." (PMID 38474073, 2024). "Overexpression of each mutant form of desmin individually led to a decrease in muscle contraction generation and morphological changes characteristic of patients with myofibrillar myopathy." (PMID 40007819, 2024). "We observed desmin aggregation, focal myofibrillar dissolution, and mitochondrial accumulation in striated muscles, which are common characteristics of myofibrillar myopathy." (PMID 35942699, 2022). "In sarcomere-related RCM, the p.Pro209Leu mutation in the BAG3 gene leads to early-onset RCM and myofibrillar myopathy with typical intra-sarcoplasmic bodies composed of BAG3 protein and desmin aggregates." (PMID 33429969, 2021). "Four horses were later found to have histochemical characteristic of abnormal aggregates of desmin within muscle biopsies suggestive of myofibrillar myopathy (MFM)." (PMID 30183782, 2018). "These ultrastructural abnormalities and abnormal desmin and αB-crystallin staining are the hallmarks of myofibrillar myopathy (MFM)." (PMID 22174871, 2011). "All these myofibrillar myopathy typical features were also present in homozygous R405W desmin knock‐in mice, however, at a much more pronounced level, including the myofibrillar and protein aggregation pathology, and abnormally shaped and enlarged mitochondria." (PMID 41165044, 2025). "Mutations of the des gene can result in aberrant Desmin structures that may lead to desminopathy (DES), a type of myofibrillar myopathy." (PMID 38658362, 2024). "Consequently, both models expressing mutant forms of desmin replicate the pathogenesis of human desmin-related myofibrillar myopathy." (PMID 40007819, 2024). "In horses, myofibrillar myopathy is a late-onset disease of unknown origin characterized by poor performance, atrophy, myofibrillar disarray, and desmin aggregation in skeletal muscle." (PMID 34112090, 2021).
myofibrillar myopathy (continued). "Similarly, a p.P209L mutation in BAG3, identified in 2018 in an eight year old boy diagnosed with myofibrillar myopathy and RCM, also caused aggregation of BAG3 and desmin, Z-disc abnormalities as well as dysregulated autophagy." (PMID 33429969, 2021). "In this study we show that AAV-mediated expression of desmin mutants in mouse muscles recapitulate the aggregation features, the decrease in contractile function and the morphological changes observed in patients with myofibrillar myopathy." (PMID 23425003, 2013).
gastrointestinal stromal tumor (27 papers, 2010 to 2025). "According to WHO 2020 criteria, LMS diagnosis requires: morphological evidence of smooth muscle differentiation; immunohistochemical positivity for ≥2 smooth muscle markers (SMA, desmin, calponin); exclusion of mimics (e.g., gastrointestinal stromal tumor, malignant peripheral nerve sheath tumor)." (PMID 40388743, 2025). "To differentiate her case from a gastrointestinal stromal tumor (GIST), we evaluated actin, desmin, S100, CD117 and CD34." (PMID 24708548, 2014). "Immunohistochemical staining of the tumor was positive for CD117 and negative both for desmin and S100, leading to the diagnosis of gastrointestinal stromal tumor." (PMID 38779196, 2024). "Bcl-2 and vimentin are typically immunoreactive in SFTs in addition to CD34 and STAT6, but SMA and desmin (a marker for myocytes), S-100 and synaptophysin (a marker for perineural tissue), or c-kit (a marker for gastrointestinal stromal tumors) are generally negative." (PMID 39435031, 2024). "Immunohistochemical staining was positive for CD34 but negative for S-100, c-kit, β-catenin, and desmin, suggesting a mesenchymal neoplasm such as a gastrointestinal stromal tumor (GIST) of the pelvis originating from the rectum." (PMID 35676716, 2022). "The tumor cells of the gastrointestinal stromal tumor were positive for H-caldesmon and CD117, weakly positive for smooth muscle actin and DOG-1, and negative for desmin, S-100 protein, CD31, and AE1/AE3." (PMID 33512639, 2021). "Desmin and C-Kit (CD117) were consistently negative, helping to exclude inflammatory myoglandular polyp and gastrointestinal stromal tumour respectively." (PMID 29463272, 2018). "The tumor cells are often positive for CD34, CD99, vimentin and BCL-2, and negative for CD117 (in gastrointestinal stromal tumors), smooth muscle actin (SMA) and desmin (in smooth muscle tumors) and S-100 protein (in nerve sheath tumors)." (PMID 25884588, 2015). "Immunohistochemistry showed focal cytoplasmic positivity for desmin, confirming smooth muscle differentiation, while staining for CD117, DOG1, CD34, cytokeratin, and S100 was negative, excluding epithelial, neural, and gastrointestinal stromal tumors." (PMID 41281033, 2025).
PEComas (23 papers, 2007 to 2025). "PEComas are immunoreactive for both smooth muscle (desmin, SMA, muscle-specific-actin, muscle myosin, and calponin) and melanocytic (HMB-45, Melan-A/MART-1, tyrosinase, and MITF) markers." (PMID 39759135, 2024). "The immunoreactivity of HMB45, SMA, Melan-A, Vimentin, and Desmin in PEComas has been extensively discussed, along with the progression of TFE3 staining positivity in PEComas." (PMID 38689335, 2024). "This case differed from otherreported TFE3-rearranged PEComas in that immunostaining showed positivityfor desmin and TFE3." (PMID 35699228, 2022). "Since PEComas are almost always immunoreactive for smooth muscle (actin, desmin, caldesmon) markers, as well as melanocytic (HMB-45, melan-A, MiTF) markers, this characteristic immunohistochemical profile provides accurate diagnosis." (PMID 34442003, 2021). "Desmin was positive in 90% of PEComas and h-Caldesmon was positive in 57% of cases." (PMID 38664269, 2024). "Desmin or caldesmon expression is observed in about 30% of cases, especially in sclerotic PEComas." (PMID 31309284, 2020). "Additionally, 31% of PEComas showed at least focal desmin staining in a recent review of all reported cases up to 2005 (61 cases), and therefore desmin staining of uterine epithelioid tumors with clear cell areas and HMB-45 positivity does not exclude the diagnosis of PEComa." (PMID 18053181, 2007). "PEComas are distinguished by the expression of smooth muscle markers (e.g., SMA, h-caldesmon, desmin) and melanocytic markers (e.g., HMB-45, melan-A, MITF)." (PMID 40002892, 2025). "Immunohistochemically, PEComas are positive for both smooth muscle markers (e.g., SMA, h-caldesmon, desmin) and melanocytic markers (e.g., HMB45, melan-A, tyrosinase, MITF)." (PMID 40002892, 2025). "Gynecologic perivascular epithelioid cell tumors (PEComas) are rare mesenchymal neoplasms characterized by the co-expression of melanocytic markers (HMB-45 and Melan-A) and smooth muscle markers (SMA, desmin, and caldesmon)." (PMID 40647483, 2025). "PEComas are characterized by the immunoexpression, among others, of both melanocytic markers (HMB-45, Melan-A, MiTF, and PNL2) and myoid markers (desmin, smooth muscle actin, muscle-specific actin, myosin, and calponin)." (PMID 40647483, 2025). "In a study aiming to distinguish PEComas from uterine smooth muscle tumors, twenty-one uterine PEComas and 45 SMTs were analyzed for PNL2; HMB45, Melan-A, Cathepsin-K, Desmin, and h-Caldesmon." (PMID 38664269, 2024). "Since PEComas are nearly always immunoreactive for both melanocytic (HMB-45, melan-A, MiTF) and smooth muscle (actin, desmin, caldesmon) markers, characteristic histologic and immunohistochemical findings provide the most accurate means of diagnosis." (PMID 28270196, 2017). "PEComas usually show immunoreactivity for both melanocytic (HMB-45 and/or melan-A) and smooth muscle (actin and/or desmin) markers." (PMID 24410788, 2014). "TFE3-rearranged PEComas that exhibit strong TFE positivity and minimal desmin and actin positivity have also recently been described." (PMID 24735727, 2014). "Almost all the PEComas were identified to be strongly positive for melanocytic markers (HMB-45 and/or melan-A) and smooth muscle markers (SMA and/or desmin)." (PMID 24348838, 2014). "Nearly all PEComas show immunoreactivity for both melanocytic (HMB45 and/or Melan-A) and smooth muscle (actin and/or desmin) markers." (PMID 22953133, 2012). "Histologically, PEComas are composed by a hybrid tumor cell which is characterized by immunoreactivity for both melanocytic (HMB45 and/or Melan-A) and smooth muscle (α-smooth muscle actin and/or desmin) markers." (PMID 22957287, 2012). "Immunohistochemically, the majority of smooth muscle tumors express strong positivity for desmin, whereas PEComas are usually desmin-negative or express desmin only focally." (PMID 23276164, 2012).
PEComas (continued). "Therefore, nearly all PEComas are immunoreactive for HMB-45 and/or Melan-A, and many are positive for smooth muscle actin, whereas desmin staining appears to be somewhat less common." (PMID 18053181, 2007). "Perivascular epithelioid cell tumors (PEComas) are a rare group of mesenchymal neoplasms composed of distinctive epithelioid cells that exhibit dual myomelanocytic differentiation, typically co-expressing melanocytic markers such as HMB-45 and smooth muscle markers including desmin or actin." (PMID 41328270, 2025). "Lack of immunoreactivity for HMB45, melan-A, desmin, pan-CK, PAX8, and S100 excluded the possibility of perivascular epithelioid cell tumor, clear cell sarcoma, metastatic renal cell carcinoma, granular cell tumor, and paraganglioma." (PMID 35626258, 2022).
smooth muscle tumor (23 papers, 2011 to 2025). A benign or malignant myomatous neoplasm arising from smooth muscle. "Epithelioid leiomyoma is a benign smooth muscle tumor characterized by uniform spindle cells with eosinophilic cytoplasm and positivity for smooth muscle markers such as desmin and smooth muscle actin (SMA)." (PMID 40578241, 2025). "Prior reports of abdominal leiomyomas show characteristic staining of smooth muscle tumors such as desmin and smooth muscle actin (SMA) in addition to CD117, estrogen receptor (ER), and progesterone receptor (PR)." (PMID 39347247, 2024). "SMA (smooth muscle antibody) (97.2%) and Desmin (94.5%) are positive in most smooth muscle tumor patients, serving as markers of smooth muscle cells and being helpful in confirming myogenic tumors." (PMID 39711950, 2024). "Some cases can show desmin positive expression, which may lead to a misdiagnosis of a smooth muscle tumor." (PMID 23148444, 2012). "Conversely, negative staining for CD117, CD34, DOG-1, smooth muscle actin (SMA), and desmin effectively excluded GIST and smooth muscle neoplasms." (PMID 40840072, 2025). "Immunohistochemically, similarly to other smooth muscle tumors, DPL is typically positive for desmin that is rarely expressed in GIST." (PMID 35885469, 2022). "An immunohistochemical panel that includes CD10 and at least two smooth muscle markers such as desmin, caldesmon, and HDAC8 is helpful in the differential diagnosis of smooth muscle tumors from ESS." (PMID 28968994, 2017). "Desmin and α-SMA are used to exclude smooth muscle tumors, and CD34 and CD117 (c-kit) are used to exclude GIST." (PMID 21418642, 2011). "In our case, the absence of CD117 and DOG1 effectively ruled out GIST, while the lack of S100 and SOX10 expression argued against malignant peripheral nerve sheath tumor, and negative SMA/desmin excluded smooth muscle tumors." (PMID 41246769, 2025). "Esophageal schwannoma cells were positive for S100 protein but negative for smooth muscle markers such as actin and desmin, which were positive in smooth muscle tumors, while CD34 and CD117 were characteristically positive in GIST." (PMID 40308497, 2025).
lymphoma (20 papers, 2009 to 2025). A malignant (clonal) proliferation of B- lymphocytes or T- lymphocytes which involves the lymph nodes, bone marrow and/or extranodal sites. "However, other lymphoma markers like CD3, cyclin D1, cytokeratin, epithelial membrane antigen (EMA), vimentin, B-cell lymphoma 2 (BCL2), CD117, CD34, desmin, and smooth muscle actin (SMA) were positive only in 1 case each." (PMID 36511607, 2023). "Other unusual circumstances contributing to misinterpretation include a include a synaptophysin, chromogranin and CD56 (keratin, desmin and WT1 negative) mesenteric ES (EWSR1-FLI1 positive) and numerous tumor-associated lymphocytes in an ELS originally diagnosed as lymphoma." (PMID 34698236, 2021).